BNIP3 (BCL2 interacting protein 3)
Diseases named in the same sentence as BNIP3 in open-access papers (continued):
Sharing a sentence is not in itself a finding about the gene and the disease.
mitochondrial disease (1 paper, 2024). "The SCFFBXL4 ubiquitin ligase complex suppresses mitophagy by controlling the degradation of BNIP3 and NIX mitophagy receptors, and FBXL4 mutations result in mitochondrial disease as a consequence of elevated mitophagy." (PMID 38992176, 2024).
skin disorder (1 paper, 2017). Any deviation from the normal structure or function of the skin or subcutaneous tissue that is manifested by a characteristic set of symptoms and signs. "Our study thus might provide new insights into the functions of BNIP3 in the pathogenesis of UVB-induced skin disorders and highlight potential targets for therapeutic interventions." (PMID 28151469, 2017).
BNIP3 also shares sentences with these, for which no sentence is quoted: Alzheimer disease (3 papers); lung adenocarcinoma (3); nasopharyngeal carcinoma (3); sarcoma (3); type 2 diabetes (3); acute myelogenous leukaemias (2); acute myocardial infarction (2); central nervous system diseases (2); endothelial dysfunction (2); kidney failure (2); lymph node (2); neurodegenerative disease (2); stomach cancer (2); uveal melanoma (2); acute lymphocytic leukaemia (1); acute respiratory distress syndrome (1); Adrenal Gland (1); alcoholic cirrhosis (1); amyotrophic lateral sclerosis (1); Anxiety (1); arteriopathy (1); asphyxia (1); astrocytoma (1); Atrophy (1); bacterial infections (1); behavioral disorders (1); Burkitt lymphoma (1); cervical squamous cell carcinoma (1); chronic kidney disease (1); chronic myeloid leukemia (1).
A further 48 diseases each share a sentence with BNIP3 in 1 paper.